BRAF (B-Raf proto-oncogene, serine/threonine kinase)
Diseases named in the same sentence as BRAF in open-access papers (continued):
Sharing a sentence is not in itself a finding about the gene and the disease.
melanoma (continued). "In summary, we have found that RIP1 plays an important role in intrinsic and acquired resistance of melanoma cells to apoptosis induced by BRAF/MEK inhibitors through activation of NF-κB." (PMID 29880840, 2018). "Nevertheless, the combination provoked a better response of intracranial BRAFV600-mutant brain metastases from melanoma (clinical trial NCT01266967) compared to monotherapies based on the BRAF inhibitor." (PMID 30053879, 2018). "Targeted therapies using BRAF inhibitors can successfully block oncogenic signaling in BRAF-mutant melanomas, leading to significant improvement in progression-free survival (PFS) and overall survival." (PMID 29929490, 2018). "An additional example of a successful translational study from mice to humans is the one demonstrating the anti-tumor activity of another BRAF inhibitor, the Dabrafenib, against human melanoma xenografts." (PMID 29534457, 2018). "It is therefore possible that a short withdrawal of the BRAF inhibitor after progression will be sufficient to lead to regression of the drug-dependent resistant melanoma cells." (PMID 30344946, 2018). "Median time to progression (TTP) and progression free survival (PFS) in 28 patients with melanoma according to BRAF and MMP-9." (PMID 30154717, 2018). "In this study, we provide evidences that melanoma CSCs are able to tolerate the pharmacological inhibition of BRAF and MEK, a process sustained by the increased function of SCD1." (PMID 30558661, 2018). "A multi‐drug phase II clinical trial including pan‐FGFR inhibitor (BGJ398) together with a MEK inhibitor (MEK162) and a RAF inhibitor (LGX818) is currently ongoing in advanced BRAF melanoma (NCT02159066)." (PMID 29463565, 2018). "To assess concordance between our UACC melanoma cell lines and the CCLE melanoma cell lines, we compared NLME curve fits by subdividing the cell lines by BRAF and NRAS mutation status in both data sets." (PMID 29435161, 2018). "For example, the use of drugs to target the protein product of the BCR–ABL translocation in chronic myeloid leukemia, or the BRAF gene in malignant melanoma, helped transform the treatment of these diseases and substantially improve survival rates." (PMID 29423044, 2018). "While activating mutations in the BRAF gene were discovered in around 50% of melanoma patients, mutations in NRAS account for 21–28% of melanomas." (PMID 29534457, 2018). "Further, due to different transcription pathway activation in melanoma cells, several other mechanisms of resistance to BRAF inhibition have been identified." (PMID 30544808, 2018). "Of note, nivolumab plus ipilimumab received approval for use in BRAF V600 wild-type metastatic/unresectable melanoma, making it the first combination checkpoint inhibition regimen to be approved by the FDA." (PMID 29769148, 2018). "In BRAF-mutant melanoma cells, ACY-1215 sensitizes vemurafenib-induced cell proliferation inhibition and apoptosis through induction of ER stress and inactivation of ERK14." (PMID 30050135, 2018). "Together, FGF1 has beneficial effects on melanoma cells and fibroblasts, thereby limiting the efficacy of BRAF inhibition." (PMID 30237393, 2018). "For example, pancreatic cancers and melanoma cell lines, which have aberrantly active MEK signaling due to oncogenic KRAS and BRAF mutations, were modeled and are predicted to be the most responsive." (PMID 30323222, 2018). "Further, even in settings like BRAF mutant melanoma and EGFR mutant non-small-cell lung cancer (NSCLC), where effective precision therapies have been established, targeted therapies often yield incomplete and transient responses." (PMID 29700304, 2018). "In line with previous results, depletion of USP28 in all the melanoma cell lines tested resulted in increased stabilization of BRAF and enhanced downstream MAPK activation." (PMID 29880484, 2018).
melanoma (continued). "A375 cells were treated either with vemurafenib, the standard treatment for BRAF-mutant melanomas, or with δ-TT; at the end of the treatments, treatment-escaping cells were replated in stem cell medium." (PMID 29330434, 2018). "The discovery of BRAF alterations in CRC excited the field with the potential to repurpose vemurafenib from melanoma to CRC." (PMID 30038711, 2018). "Our work completes an ERK/SOX10/FOXD3/ERBB3 pathway that governs the FOXD3-mediated adaptive resistance to RAF/MEK inhibitors in mutant BRAF melanoma." (PMID 29295999, 2018). "In melanoma, the MAPK pathway is hyper-activated in up to 75% of cases, primarily due to somatic-gain-of function mutations in BRAF (~50% of cases) or RAS (~25% of cases)." (PMID 29946532, 2018). "In a non-randomized, open-label phase II study of advanced melanoma patients harboring NRAS or VAL600 BRAF mutations, binimetinib showed a partial response, providing the first target therapy to treat patients with NRAS-mutated melanomas." (PMID 29455659, 2018). "AMPK phosphorylation was markedly higher in both BRAF wild type cells (Mewo and SK-MEL-2) compared with melanomas harboring the BRAFV600E mutation." (PMID 30651927, 2018). "We exposed BRAF-mutant, therapy-sensitive, melanoma cell lines (M249 and A375) to vemurafenib and profiled their transcriptome by RNA-seq." (PMID 29950559, 2018). "This was reversed by co-overexpression of RIP1, suggesting that downregulation of CYLD is responsible for upregulation of RIP1 in melanoma cells with acquired resistance to BRAF inhibitors." (PMID 29880840, 2018). "We examined the effect of fisetin on endogenous levels of YB-1 in highly aggressive BRAF mutant melanoma cells." (PMID 30356079, 2018). "Briefly, 58/124 (46.8%) primary melanomas and 70/150 (46.7%) metastatic tissues presented mutations in BRAF gene, whereas NRAS mutations were found in 19/124 (15.3%) primary tumors and 24/150 (16.0%) melanoma metastases." (PMID 29492214, 2018). "The majority of melanomas constitutively express oncogenic BRAF and/or NRAS, driving malignant proliferation." (PMID 29716947, 2018). "Loss of ICAM-1 protein and mRNA expression was a strong prognosticator of diminished survival in BRAF/NRAS mutant melanoma." (PMID 30116025, 2018). "An important finding of this study is that melanoma cells with acquired resistance to BRAF inhibitors are more critically dependent on RIP1 for survival." (PMID 29880840, 2018). "This better response of NRAS-mutated melanoma to immune therapy is due to a higher level of immunosuppression in the tumor microenvironment compared to BRAF-mutant melanoma." (PMID 30360441, 2018). "Secondary mutations in MEK and activation of downstream MEK1 following escape from single agent BRAF inhibition led to the investigation of the current SOC therapy for BRAFV600E/K-mutant melanoma, dual dabrafenib and trametinib treatment." (PMID 29541385, 2018). "Strikingly, results of this study reveal that this finding holds true for NRAS and BRAF mutant, as well as ‘wild type’ melanoma cells." (PMID 30405888, 2018). "Although melanocytic proliferations are less frequent than squamoproliferative lesions, changes in preexisting nevi, new melanocytic nevi, and new primary melanomas have been reported in patients receiving BRAF inhibitors." (PMID 30693134, 2018). "In a previous study, we tested a patient-derived orthotopic xenograft (PDOX) nude mouse model of BRAF V600E-mutant melanoma and observed the efficacy of rMETase." (PMID 29416666, 2018).
melanoma (continued). "Inhibition of the BRAF/MEK pathway in melanomas constitutes an important treatment option for BRAF-mutant melanomas." (PMID 30237393, 2018). "Illustrating this, BRAF V600E and NRAS Q61R appeared to be selected more strongly than KRAS G12D in melanoma and thyroid cancer, but more weakly than this mutation in pancreatic cancer." (PMID 29748584, 2018). "Recent studies have shown EZH2 to be an oncogene in BRAF-driven melanoma, and combination therapy of the BRAF inhibitor vemurafinib with JQ1 or DNA methyltransferase inhibitor decitabine displayed efficacy in pre-clinical melanoma models." (PMID 30340362, 2018). "We have previously shown that an FDA approved drug leflunomide, used for rheumatoid arthritis (RA), also holds potential therapeutic value in treating melanoma especially if used in combination with the mutant BRAF inhibitor, vemurafenib." (PMID 29423085, 2018). "HMEX were isolated from supernatants of six melanoma cell lines (3 BRAF V600E mutant cell lines and 3 BRAF wild-type cell lines) using ultracentrifugation or Size Exclusion Chromatography (SEC)." (PMID 30150674, 2018). "Silencing of CDK16 in both BRAF‐ and NRAS‐mutant melanoma cell lines led to cell cycle arrest associated with expression of p27 and reduced phosphorylation of the RB protein at S780." (PMID 29112787, 2018). "Alternatively, activation of wild-type BRAF (BRAFWT) and CRAF can occur through activating mutations in NRAS, or KIT, or and through NF1 deletion, which occur in approximately 20% of melanomas." (PMID 29481571, 2018). "His medical history included hypertension and multiple relapsed stage IV BRAF gene mutant malignant melanoma involving skin, liver and spleen for 11 years." (PMID 30255823, 2018). "In contrast, we demonstrated that recombinant methioninase (rMETase) which targets the general metabolic defect in cancer of methionine dependence, was effective against the BRAF-V600E mutant melanoma PDOX model." (PMID 29416666, 2018). "For the TGen melanoma cell lines, WGCNA modules were created using BRAF and KRAS mutation groupings." (PMID 30042785, 2018). "Studies using a mouse model of BRAFV600E mutant melanoma showed that PD-1 or PD-L1 blockade combined with BRAF inhibition enhanced the activity of TILs and prolonged survival." (PMID 29482595, 2018). "In contrast, adifferent member of the FOX family, the stem cell transcription factor forkheadbox D3 (FOXD3) has been identified as an adaptive mediator of the response toMAPK pathway inhibition selectively in mutant BRAF melanomas." (PMID 29615030, 2018). "Novel therapies are undergoing clinical trials, for example, the Hsp90 inhibitor, XL888, in combination with BRAF inhibitors for the treatment of therapy‐resistant melanomas." (PMID 29507054, 2018). "This strong implication of NF1 in the drug resistance acquisition is reinforced by the evidence that NF1 mutations are coupled with drug resistance also in a human setting, in BRAF-mutant melanoma patients." (PMID 29534457, 2018). "The anti-proliferative effects of both SR4 and niclosamide were evaluated in melanoma cells with wild type BRAF (Mewo, SK-MEL-2), BRAFV600E (A101D, A375, A2058, SK-MEL5, SK-MEL-28) and NRAS (SK-MEL-2) mutations using the Cell Titer Glo cell viability assay." (PMID 30651927, 2018). "Here, the authors show that ERK1/2 mediated phosphorylation regulates sumoylation of SOX10 which activates FOXD3, and depletion of SOX10 sensitises BRAF mutant melanoma cells to RAF inhibitors." (PMID 29295999, 2018). "One of these patients and two others subsequently developed distant metastases in lung (single 7‐mm lesion, subsequently resected revealing BRAF V600E melanoma, undetected by ctDNA), liver (BRAF V600E, detected), and kidney (NRAS Q61R, detected)." (PMID 30113761, 2018). "Meanwhile, few animal models exist for uncommon molecular or histological melanoma subtypes such as BRAF wild-type (BRAFwt) or mucosal melanoma." (PMID 30188888, 2018).
melanoma (continued). "Genotyping of melanomas is used to identify patients for treatment with BRAF and MEK inhibitors, but clinical responses are highly variable." (PMID 30116025, 2018). "Several groups have found that BRAF inhibitor-resistant melanoma cell lines can recover ERK phosphorylation independently of the presence of BRAF inhibitors, and the same remains true for the classic chemotherapeutic drug dacarbazine (DTIC)." (PMID 30191142, 2018). "Vemurafenib and dabrafenib are widely used in clinical practice for the treatment of BRAF‐mutant melanoma." (PMID 29112787, 2018). "In this study, the authors demonstrate that SREBP-1-mediated induction of lipid biosynthesis contributes to therapy resistance in BRAF mutant melanoma." (PMID 29950559, 2018). "We used a BRAF wild type cutaneous melanoma tumor as a model as patients with this type of melanoma generally have limited therapeutic options." (PMID 29464063, 2018). "As FGFs are potent growth factors with multiple effects on different cell types of the melanoma microenvironment, we were interested to investigate if other FGFs are induced by BRAF inhibition in melanoma cells in addition to FGF1." (PMID 30237393, 2018). "In most cases BRAF resistant melanomas bear additional mutations reactivating MAPK pathway, e.g., MEK1 mutations, and BRAF or KRAS amplification." (PMID 29371600, 2018). "Further studies with a p-ERK inhibitor, PD98059, confirmed that inhibition of p-ERK can reverse the BRAF inhibition in those BRAF inhibitor-resistant melanoma cells." (PMID 29929490, 2018). "Similar survival trends were also observed for this molecular phenotype using the TCGA-SKCM dataset mRNA transcript level information of Stage III NRAS/BRAF melanoma specimens." (PMID 30116025, 2018). "Taken together, our data indicate that while the effect of haplo-deficient Phd2 is weaker than that of biallelic deletion of Phd2, it is still sufficient to cooperate with mutant BRAF to induce melanoma." (PMID 30575721, 2018). "Here we show that melanoma cells treated with the BRAF inhibitor vemurafenib secrete factors, which stimulate naive melanoma cells and fibroblasts, thereby limiting the anti-tumorigenic effect of BRAF inhibition." (PMID 30237393, 2018). "A majority of patients with a V600x melanoma respond quickly to BRAF/MEK inhibition (BRAFi/MEKi) and have an obvious clinical benefit." (PMID 29682188, 2018). "We evaluated the efficacy of rMETase and rMETase in combination with TEM on the BRAF-V600E-negative melanoma." (PMID 29416666, 2018). "Currently, there are two BRAF mutation inhibitors (vemurafenib and dabrafenib) that are approved by the U.S. FDA to treat stage 3 or 4 melanoma with positive BRAFV600E or BRAFV600K mutation." (PMID 30651927, 2018). "Next to the more common BRAF oncogene, mutations in the NRAS gene result in more aggressive melanomas." (PMID 30360441, 2018). "We used the human A375 BRAFV600E mutant melanoma xenograft model to assess the in vivo efficacy of the two uncouplers in comparison with the BRAF inhibitor vemurafenib." (PMID 30651927, 2018). "ABCB5 was differentially expressed in early passages of TMZ-treated and BRAF inhibitor-treated melanoma cells." (PMID 29929490, 2018). "The combination of BRAF/MEK inhibitors have been shown to extend PFS and OS in BRAF-mutated metastatic melanoma but melanoma cells express low levels of EGFR activity." (PMID 30519549, 2018). "Our work provides further insight into the role of ABCB5 in BRAF inhibitor-resistant melanoma cells." (PMID 29929490, 2018). "Columbus Study (phase III study with encorafenib + binimetinib vs. vemurafenib or encorafenib in BRAF-mutant melanomas): Data were presented after 18 months of follow-up." (PMID 30595751, 2018).
melanoma (continued). "Although the effect of haplo-deficiency of Phd2 in melanocytes is relatively weaker than that exhibited when biallelic deletion of Phd2 occurs, it is still sufficient to cooperate with oncogenic BRAF to induce melanoma." (PMID 30575721, 2018). "As seen in melanoma, the inhibition of the Raf stimulating effect of PTPIP51 can be used as a counter-regulatory mechanism against the BRAF deregulation within the sequence from normal nevi over dysplastic nevi to melanoma." (PMID 30360441, 2018). "We previously demonstrated that BRAF mutant (mt) melanoma cells exposed to sub-lethal concentrations of a drug, hypoxia or nutrient starvation for 12 to 15 days convert into multi-drug tolerant cells." (PMID 29492189, 2018). "Although the BRAF inhibitors dabrafenib and vemurafenib have both proven successful against BRAF‐mutant melanoma, there seem to be differences in their mechanisms of action." (PMID 29112787, 2018). "This study compared pembrolizumab and investigator-choice chemotherapy (ICC) for the treatment of unresectable stage III or stage IV ipilimumab and/or BRAF inhibitor-refractory melanoma." (PMID 29357948, 2018). "For example, in a study on BRAF-mutated malignant melanoma, treatment of BRAF-inhibitor led to the proliferation of clones of KRAS mutation, BRAF gene amplification, and PTEN gene loss, at different sites within a lesion." (PMID 29932159, 2018). "We analysed the chemosensitivity of melanoma cells with acquired resistance to BRAF inhibitor (vemurafenib) (R) or combined BRAF and MEK inhibitor (vemurafenib and trametinib) (DR) treatment and of their sensitive (S) counterparts." (PMID 30206212, 2018). "Strikingly, this was consistently observed in NRAS and BRAF mutant, as well as in ‘wild type’ melanoma cells." (PMID 30405888, 2018). "A role of PGC1α in preventing melanoma metastasis was shown with treatment with a BRAF inhibitor, which upregulated PGC1α and its downstream target DNA-binding protein inhibitor-2 (ID-2), which in turn led to suppression of metastasis-related genes." (PMID 29361779, 2018). "RAS/RAF/MEK/ERK pathway vertical inhibition in treatment of V600 BRAF mutant melanoma is already approved in clinical practice." (PMID 29739364, 2018). "We previously compared differences in gene expression between parental and BRAF mt melanoma IDTCs (WM164) and identified significant changes in epigenetic factors leading to an altered chromatin state." (PMID 29492189, 2018). "Melanoma is the most aggressive skin cancer and is responsible for 80% of the skin cancer-related death despite several targeted therapies, such as BRAF and MET inhibitors, have been developed." (PMID 29970086, 2018). "Our laboratory previously showed that ectopic expression of Grm1 is sufficient to induce spontaneous melanoma formation with 100% penetrance in transgenic mouse model, TG-3, which harbors wild-type BRaf." (PMID 29464040, 2018). "Several studies have demonstrated the existence of a correlation between ctDNA kinetics and melanoma response to BRAF inhibitors and to anti-PD1 antibodies." (PMID 29861869, 2018). "Similar results are available for other cancer genes, such as BRAF in melanoma, BRCA1 and PIK3CA in breast cancer." (PMID 29485617, 2018). "Other findings of this study showed toxicities in GEMMs for melanoma, but increased survival benefits after treatment with TM alone or in combination with a BRAF inhibitor, vemurafenib." (PMID 33912613, 2018). "Here we validated the effect of fisetin on YB-1 and evaluated its interaction with RSK in BRAF-mutant melanoma cells." (PMID 30356079, 2018). "Blocking of MAPK signaling using specific small molecule inhibitors of BRAF and MEK are central in the treatment of BRAF mutant melanoma patients." (PMID 30405888, 2018). "In the observation arm, BRAF mutant melanoma patients had poorer OS compared with BRAF wild-type melanomas (P = 0.06)." (PMID 30010756, 2018).